KLF5 (KLF transcription factor 5)
Diseases named in the same sentence as KLF5 in open-access papers (continued):
Sharing a sentence is not in itself a finding about the gene and the disease.
prostate carcinoma (continued). "The chemokine receptor CXCR4, a direct transcriptional target of KLF5, is subsequently activated and binding of its ligand CXCL12 (CXCL12, also known as SDF-1α) underlies the preferential chemotactic migration of prostate cancer cells to organ sites with elevated levels of CXCL12, for example bone." (PMID 24429391, 2014). "This tumor suppressing role of KLF5 has been suggested in clinical breast and prostate carcinomas, where loss of KLF5 was observed when compared to normal tissue counterparts." (PMID 24429391, 2014). "Taken together with previous findings of context-dependent functions of KLF5 in cell proliferation and frequent deletion of KLF5 in human prostate cancer, these results suggest that KLF5 plays an important role in the proliferation, differentiation and tumorigenesis of prostate epithelial cells." (PMID 23755247, 2013). "In addition, ectopic expression of KLF5 in prostate cancer cells inhibits cell proliferation and suppresses tumorigenesis in a xenograft model." (PMID 23755247, 2013). "We are currently testing whether simultaneous deletion of Klf5 and other genes that are frequently deleted in human prostate cancer, including PTEN at 10q23 and NKX3-1 at 8p21, could induce tumorigenesis." (PMID 23755247, 2013). "However, it remains unclear whether and how KLF5 acetylation remodels the TME in prostate cancer progression." (PMID 38781024, 2024). "Therefore, this study indicates that KLF5 acetylation is a barrier to tumor progression boosted by PTEN deficiency and provides evidence for a PTM as an essential molecular event induced by PTEN inactivation to stall prostate cancer progression." (PMID 38781024, 2024). "However, a recent study depicted a tumor-suppressor role for KLF5 in prostate cancer." (PMID 35317831, 2022). "Therefore, as a single agent inhibiting TGF-β signaling and Bcl-2 expression, naftopidil could be an effective inhibitor of the TGF-β/acetylated KLF5 signaling axis for overcoming DTX resistance in prostate cancer." (PMID 32685011, 2020). "However, whether the downregulation of KLF5 relates to the response of prostate cancer cells to chemotherapy and prognosis of patients is still unknown." (PMID 31534497, 2019). "Interestingly, we found that KLF5 could inhibit prostate cancer cell autophagy via suppressing the transcription of BECN1 cooperatively with HDAC3." (PMID 31534497, 2019). "Interestingly, KLF5 could inhibit prostate cancer cell autophagy by suppressing the transcription of BECN1 cooperatively with HDAC3." (PMID 31534497, 2019). "Since data on the relationship between gene expression levels and tumor sensitivity to docetaxel is non-existent or scarce, it is difficult to analyze whether KLF5 expression level is associated with tumor response to docetaxel in prostate cancer patients." (PMID 31534497, 2019). "On the contrary, KLF5 overexpression increased the sensitivity of prostate cancer cells to docetaxel, suggesting that expression level of KLF5 in prostate cancer might be indicative of the cancer response to docetaxel treatment; the threshold of the KLF5 level remains to be identified though." (PMID 31534497, 2019). "Based on our finding that manipulation of KLF5 expression in human prostate cancer cells affected tube formation and migration of HuVECs, we further tested whether manipulation of KLF5 expression also affects the expression of HIF1α and other pro-angiogenic factors as in mouse tissues." (PMID 25896712, 2015). "KLF5 might function differently and organ-specifically in prostate cancer and bladder cancer." (PMID 26544730, 2015). "Thus whether KLF5 acetylation levels are different between prostate cancer and bladder cancer and between PTEN deleting statuses remain to be clarified." (PMID 26544730, 2015). "In addition, KLF5 was shown to center the deletion at 13q21 in human prostate cancer." (PMID 23755247, 2013).
prostate carcinoma (continued). "Of note, there have previously been links between KLF5 expression and SP1 in breast and prostate cancers, linking elevated KLF expression with tumour suppressive functions." (PMID 39748426, 2025). "Acetylated KLF5 (Ac-KLF5) and its downstream effectors are thus potential therapeutic targets for treating TGF-β-induced bone metastasis in prostate cancer." (PMID 36810084, 2023). "In this study, we adopted an in vitro spheroid invasion screening assay to prostate cancer cells expressing KLF5K369Q, a mutant mimicking Ac-KLF5." (PMID 36810084, 2023). "The Ac-KLF5-mimicking KLF5K369Q mutant maintains EMT, promotes cell invasion, and induces bone metastasis in prostate cancer cells." (PMID 36810084, 2023). "Further analysis revealed that NTZ binds to the KLF5 protein, while the modified KLF5 is bound to the promoter region of MYBL2, a gene known to promote bone metastasis in prostate cancer, to activate its transcription." (PMID 38260135, 2023). "A spheroid invasion assay was applied to prostate cancer cells expressing KLF5K369Q, which mimics Ac-KLF5, to screen 1987 FDA-approved drugs for invasion suppression." (PMID 36810084, 2023). "For example, two Ac-KLF5-upregulated and NTZ-downregulated genes, MYBL2 and TIMM8A, were upregulated in human prostate cancer." (PMID 36810084, 2023). "For example, acetylation of KLF5 can maintain EMT and carcinogenicity, thereby promoting chemoresistance in prostate cancer." (PMID 35614040, 2022). "Examination of molecular pathways demonstrates that KLF5 inhibits BECN1 and HDAC3 (histone deacetylase 3) cooperation to suppress autophagy and promote docetaxel sensitivity in the context of prostate cancer." (PMID 35317831, 2022). "In contrast to the reported results in the DU145 prostate cancer cell line 34, both TSA and SAHA reduced KLF5 protein expression levels in HCC1937 and HCC1806 cells in a time-dependent manner." (PMID 35342356, 2022). "In prostate cancer (PCa), bone-borne TGF-β was found to promote the acetylation of KLF5, leading to osteoclastogenesis and chemoresistant bone metastatic formation." (PMID 36577755, 2022). "Increasing evidence has demonstrated that upstream mediators such as AMPK, non-coding RNAs, KLF5, MTOR and others regulate autophagy in prostate cancer." (PMID 35317831, 2022). "The transcription factors Krüppel-like factor 5 and 6 (KLF5 and KLF6) are critically involved in prostate cancer progression." (PMID 33572160, 2021). "In short, based on the findings in two prostate cancer patient datasets, a high level of TGF-β induced a shorter survival time in patients with high KLF5 mRNA level." (PMID 32685011, 2020). "Next, we aimed to explore the mechanism of DTX resistance mediated by acetylated KLF5 and TGF-β in prostate cancer cells." (PMID 32685011, 2020). "However, why KLF5 loss is associated with prostate cancer aggressiveness is still not clear." (PMID 32546700, 2020). "Analysis of 499 prostate cancer samples and 57 mCRPC samples demonstrated that higher TGF-β signaling activity is prognostic of shorter overall survival in patients with higher KLF5 mRNA levels." (PMID 32685011, 2020). "The latest study validated RBL1, KLF5, SMAD4, and TIMP2 as the direct miR-888 targets in prostate cancer." (PMID 33123477, 2020). "Thus, our results indicated that down-regulation of KLF5 in castration-resistant prostate cancer might not only promote cell autophagy but also facilitate cell autophagy induced by docetaxel, leading to increased cell survival and reduced cell sensitivity to docetaxel." (PMID 31534497, 2019). "KLF5 knockdown resulted in lower cell sensitivity to docetaxel in C4-2 and CWR22RV1 prostate cancer cells as detected by cell viability assay." (PMID 31534497, 2019). "Therefore, KLF5 may have a tumor suppressor function in prostate cancer." (PMID 31534497, 2019).
prostate carcinoma (continued). "However, it is not known whether downregulation of KLF5 is associated with the response of prostate cancer cells to chemotherapy and/or prognosis of patients." (PMID 31534497, 2019). "To further explore the role of KLF5 in cell autophagy, we applied specific siRNA to knockdown KLF5 in C4-2 and CW22RV1 prostate cancer cell lines and examined the expression of autophagy-related markers using Western blotting." (PMID 31534497, 2019). "We found that expression of KLF5 protein was down-regulated by the p70S6K inhibitor, suggesting that p70S6K could promote KLF5 expression by enhancing initiation of its mRNA translation in prostate cancer cells and KLF5 could mediate p70S6K function in autophagy." (PMID 31534497, 2019). "Despite the functional difference, acetylation of Klf5 is regulated by TGF-β signaling in ESCs, as well as in epidermal cells and prostate cancer cells." (PMID 26372456, 2015). "While it was identified as a putative tumor suppressor in prostate cancer, likely due to its function as an effector of TGF-β in the inhibition of cell proliferation, KLF5 is unacetylated and promotes cell proliferation in the absence of TGF-β." (PMID 23755247, 2013). "This acetylated form of KLF5 (Ac-KLF5) and its downstream targets could be potential therapeutic targets for TGF-β-induced bone metastasis in prostate cancer." (PMID 38260135, 2023). "A recent study suggested that KLF5 acetylation may regulate KLF5 protein stability and that knockdown of HDAC1/2 in DU145 prostate cancer cells upregulated KLF5 protein acetylation and expression levels by blocking its degradation." (PMID 35342356, 2022). "Additionally, phospholipase Cε, Kruppel-like factor 5 (KLF5), and protein kinase D3 can directly or indirectly interact with SREBP-1 to control lipid metabolism in the occurrence and progression of prostate cancer." (PMID 35912181, 2022). "Besides, docetaxel exposure downregulates KLF5 expression via an AMPK-MTOR-RPS6KB/p70S6K axis to increase BECN1 expression, leading to autophagy induction and chemoresistance features of prostate cancer cells." (PMID 35317831, 2022). "For prostate cancer (PRAD), kidney chromophobe (KICH), and testicular germ cell tumors (TGCT), KLF5 deletion was predominant, and a decrease in KLF5 transcription could be observed (middle 3)." (PMID 33923166, 2021). "Our finding that KLF5 and AR opposition converged on a set of genes that define basal cell identity, and that KLF5 overexpression in AR-positive prostate cancer cells enhanced expression of the basal cytokeratin CK5, highlights a role for KLF5 in supporting a mixed basal/luminal cell identity." (PMID 34737261, 2021). "The reduction of KLF5 expression leads to decreased mRNA level of PDGF-A together with diminished CD31-positive region ratio, hence inhibiting angiogenesis and tumor growth of prostate cancer." (PMID 33493334, 2021). "Here, we demonstrate the stem cell transcription factor Krüppel-like factor 5 (KLF5) is low or absent in prostate cancers prior to endocrine therapy, but induced in a subset of CRPC, including CRPC displaying lineage plasticity." (PMID 34737261, 2021). "Furthermore, we performed survival analysis in prostate cancer patient conditioned on TGF-β signaling and KLF5 mRNA status." (PMID 32685011, 2020). "The correlation between KLF5/BECN1 levels and prostate cancer prognosis may be helpful toward precision medicine in the clinic by identifying prostate cancer patients, who are more likely to respond to docetaxel treatment." (PMID 31534497, 2019). "Taken together, our results indicated that KLF5 knockdown enhances docetaxel-induced cell autophagy, and repression of BECN1 and cell autophagy is necessary for KLF5 to increase cell sensitivity to docetaxel in prostate cancer cells." (PMID 31534497, 2019). "It has been demonstrated that TGF-β signaling induces acetylation of KLF5 in cultured noncancerous epithelial cells, as well as prostate cancer cell lines." (PMID 26372456, 2015).
prostate carcinoma (continued). "In addition, conventional comparative genomic hybridization (CGH) studies indicate that deletion spanning the KLF5 locus could occur in as much as 39% of prostate cancers, and our earlier deletion analyses suggest that hemizygous deletion is more common than homozygous deletion in prostate cancer." (PMID 25896712, 2015). "During the development of human prostate cancer, chromosome 13q is one of the most frequently deleted chromosomes, and the deletion involves multiple regions and genetic foci in 13q14 and 13q21, including RB1 and FOXO1 at 13q14 and KLF5 at 13q21." (PMID 25896712, 2015). "Although hemizygous deletion of KLF5 is highly frequent in human prostate cancer, no homozygous deletion was detected in hundreds of human cancer specimens, in contrast to the deletion of two other frequently deleted loci – NKX3-1 at 8p21 and PTEN at 10q23." (PMID 23755247, 2013). "In soft agar assays, the growth of AR-positive prostate cancer cells overexpressing KLF5 was suppressed by androgen withdrawal or enzalutamide treatment, and cell cycle activity was lowest in LTL-331 tumors when KLF5 expression and basal cell activity were highest." (PMID 34737261, 2021). "Additionally, genes that were positively-regulated by KLF5 in R1-AD1 cells were positively enriched in gene expression data comparing clinical NEPC vs. CRPC tissues as well as gene expression data comparing NEPC vs. primary prostate cancer tissues." (PMID 34737261, 2021). "To further detect the reduction of cell sensitivity by KLF5 down-regulation in the long-term, we performed colony formation assay and found that KLF5 knockdown significantly promoted colony formation when C4-2 and CWR22RV1 prostate cancer cells were treated with docetaxel for two weeks." (PMID 31534497, 2019). "Another significant finding was that docetaxel treatment repressed KLF5 expression through AMPK/mTOR/p70S6K signaling pathway resulting in increased BECN1, induction of cell autophagy, and promotion of cell survival in castration-resistant prostate cancer cells." (PMID 31534497, 2019). "However, our results showed that KLF5 did not alter the transcription of HIF1α either in mouse prostates or in human prostate cancer cells." (PMID 25896712, 2015). "Collectively, these data demonstrate that KLF5 overexpression regulates ERBB2 expression in AR-positive prostate cancer cells and more broadly regulates ERBB2-related genes LGALS7 and FAM129B in prostate cancer cells regardless of cellular AR status." (PMID 34737261, 2021).
colorectal cancer (44 papers, 2010 to 2025). A primary or metastatic malignant neoplasm that affects the colon or rectum. "Previous studies have suggested that KLF5 has an important role in cancer cell proliferation, and recurrent missense mutations in the phosphodegron domain of KLF5 have been identified in colorectal carcinomas." (PMID 40757636, 2025). "In colon cancer, however, not only is KLF5 important for tissue identity, but it was also reported to be haploinsufficient, potentially explaining why loss of chr13q is so rare in colorectal cancer." (PMID 38622679, 2024). "Another study showed that KLF5 knockdown in SMAD4-deficient colorectal cancer cells increases TGFβ-induced apoptosis and makes the cells more sensitive to 5-fluorouracil treatment." (PMID 37377893, 2023). "KLF5 is associated with CSC-like properties because KLF5 knockdown suppressed sphere-formation activity in colorectal cancer (CRC) cell lines." (PMID 34707247, 2022). "KLF5, another substrate of FBXW7, is necessary for the initial steps of tumor development in ApcMin and ApcMinKRASG12V mouse models of colorectal cancer, and a large proportion of the mutations of KLF5 in cancer patients are concentrated in its CPD." (PMID 32429232, 2020). "We believe the PrPC‐FOXO3a‐KLF5 axis represents a novel molecular predictor of cisplatin resistance and associated metastatic relapse in aggressive colorectal cancer." (PMID 30478887, 2019). "Moreover, the degron in KLF5 is also mutated as an alternative to FBXW7 ablation in colorectal cancer." (PMID 35328741, 2022). "In addition to KLF1, two hotspot mutations in KLF5 were found in colorectal cancer samples: one in DBD and another within a phospho-degron domain." (PMID 35996584, 2022). "However, consistent with its role as a promoter of proliferation and survival, KLF5 has been implicated as an oncogene in selected epithelial tissues, such as colorectal cancer and intestinal tumors." (PMID 26474386, 2015). "Since KLF5 has been shown to mediate the function of both APC and RAS, and mutations in APC and KRAS are common events in colorectal cancer, we examined the role of KLF5 in mediating intestinal tumor formation in mice compound for ApcMin and intestine-specific KRASV12 mutations in the current study." (PMID 20298593, 2010). "Of particular interest is KLF5, which is located on chr13q and colorectal cancer cell lines are significantly more sensitive to its knockout." (PMID 38622679, 2024). "In line with a potential driving role in the recurrence of chr13q gain in colorectal cancer, KLF5 was among the most significantly overexpressed genes in colorectal tumors and in colorectal cell lines versus all other cancer types." (PMID 38622679, 2024). "It has been shown that KLF5 inhibition can restore oxaliplatin sensitivity in patient-derived colorectal cancer organoids by restoring the apoptotic response." (PMID 37377893, 2023). "The evolving evidence suggested that GSK3β phosphorylated KLF5, thereby promoting Fbw7‐mediated KLF5 ubiquitination in colorectal cancer." (PMID 37461162, 2023). "The current review expands on the role of KLF4 and KLF5 in animal models of colorectal cancer, providing recent discoveries in their involvement in regulating the development, progression, and metastasis of CRC." (PMID 37173904, 2023). "A recent study was the first to examine the expression of levels of KLF5 in patients with colorectal cancer to determine correlation with clinical outcomes." (PMID 37173904, 2023). "Kruppel-like factor 5 (KLF5) was verified to promote anoikis resistance, and elevated KLF5 expression was correlated with poor clinical outcome in colorectal cancer patients." (PMID 37056778, 2023). "MiRs bind directly to the 3′UTR of KLF5, thereby suppressing colorectal cancer cell proliferation, migration, and stemness in vitro and inhibiting tumor growth in vivo in mouse models." (PMID 37173904, 2023).